MIR6770-2 (microRNA 6770-2)
Synonyms: hsa-mir-6770-2
Gene: MicroRNA gene on chromosome 16 (16,329,305 to 16,329,364, forward strand). Ensembl gene ENSG00000277698.
Homologues: Paralogues in human: MIR6770-1 (100% identical), MIR6770-3 (100% identical).